RNU6-950P (RNA, U6 small nuclear 950, pseudogene)
Gene: Small nuclear RNA gene on chromosome 12 (54,317,781 to 54,317,887, reverse strand). Ensembl gene ENSG00000207381.
Homologues: Orthologues: chimpanzee U6 (99% identical), macaque U6 (94% identical), pig U6 (82% identical), dog U6 (80% identical), dog U6 (75% identical). Paralogues in human: RNU6-1316P (89% identical), RNU6-116P (88% identical), RNU6-140P (88% identical), RNU6-25P (88% identical), RNU6-33P (88% identical), RNU6-378P (88% identical), RNU6-698P (88% identical), RNU6-842P (88% identical), RNU6-1 (87% identical), RNU6-2 (87% identical), RNU6-29P (87% identical), RNU6-338P (87% identical), and 1285 more.